IGF1 (insulin like growth factor 1)
Diseases named in the same sentence as IGF1 in open-access papers (continued):
Sharing a sentence is not in itself a finding about the gene and the disease.
diabetes (continued). "Identifying patients with low IGF‐1 levels could allow for targeted interventions, such as optimizing nutrition, managing comorbidities (e.g., diabetes mellitus), or using pharmacological agents to modulate IGF‐1 levels before surgery." (PMID 41199981, 2025). "Through mechanisms likely independent of IGF-1, IGFBPs appear to be strongly associated with glucose homeostasis in diabetes." (PMID 41226444, 2025). "In addition to conventional diabetes medications and dietary management, newer agents such as metreleptin and recombinant IGF-1 have been tested for treating RMS in several case reports." (PMID 40144769, 2025). "It included IGF-1, C-Peptide, age, diabetes mellitus, total cholesterol, White Matter Lesion, sex." (PMID 39963470, 2025). "Furthermore, in a preceding study, we found low IGF-1 and high IGFBP-1 levels to be predictive of the incidence of T2DM in a prediabetic cohort with a high risk for the development of diabetes." (PMID 38928106, 2024). "Notably, IGF-1 and IGFBP-3 have been implicated in developing thyroid nodules in patients with type 2 diabetes mellitus." (PMID 39444449, 2024). "Diabetes also caused reduced levels of IGF-2 and IGF-1 in the vitreous fluid." (PMID 38300646, 2024). "Intriguingly, IGF-1 levels were significantly higher in patients with uncontrolled diabetes." (PMID 39578883, 2024). "Beyond the gastrointestinal realm, the derived hypomagnesemia and reduced insulin-like growth factor-1 (IGF-1) levels might facilitate diabetes mellitus development." (PMID 38678022, 2024). "Inhibition of the GH/IGF-1 axis is also highlighted as a key strategy to enhance human health span by reducing the incidence of chronic age-related diseases, such as cancer and diabetes." (PMID 39273251, 2024). "Elevated levels of Insulin-Like Growth Factor-1 (IGF-1) were found to be associated with increasing age, longer duration of Diabetes Mellitus (DM), higher HbA1c, and higher Quantitative Insulin Sensitivity Check Index (QUICKI) value (P = 0.050, P = 0.044, P = 0.001, and P = 0.039 respectively)." (PMID 39578883, 2024). "Impaired β cell function, along with the impact of PDAC-released factors (e.g., adrenomedullin (ADM), IGF-1, and macrophage inhibitory factor (MIF) on pancreatic islets, may contribute to the induction of diabetes associated with PDAC." (PMID 39596226, 2024). "Of note, IGF-1 inhibition might be contraindicated in patients with diabetes as IGF-1 enhances insulin sensitivity by promoting glucose uptake and utilization." (PMID 39759002, 2024). "Although the linkage between diabetes and cancer is not completely understood, the biological mechanisms include hyperglycemia, hyperinsulinemia, increased bioactivity of insulin-like growth factor 1, oxidative stress, dysregulations of sex hormones, and chronic inflammation." (PMID 39188673, 2024). "Furthermore, the diabetes mellitus rat models displayed elevated levels of miR-365 and Bax expression, alongside reduced levels of Bcl-2 and IGF-1 expression." (PMID 38970639, 2024). "The precise cause of elevated IGF-1 levels in the retina due to diabetes is not completely understood at this time." (PMID 38300646, 2024). "Notably, IGF-1 concentrations were found to be elevated in patients with uncontrolled diabetes mellitus, characterized by HbA1c levels exceeding 8%." (PMID 39578883, 2024). "Increased GH (and, consequently, insulin-like growth factor 1 [IGF-1]) or increased ACTH (leading to elevated cortisol) are associated with multiple underlying conditions, including impaired glucose tolerance and diabetes." (PMID 38577574, 2024). "Additionally, since insulin and IGF-1 are functionally intertwined, the profound consequences of diabetes on insulin function heavily affect IGF-1/IGF-1R activity, and vice versa." (PMID 39638246, 2024). "IGF-1 was positively correlated with the duration of diabetes (years)." (PMID 38724932, 2024).
diabetes (continued). "However, IGF-1 therapy was able to improve metabolic control of diabetes and growth in some of these described cases but remained ineffective in others." (PMID 36331627, 2023). "As a corollary to these findings, IGF-1 supplementation and exercise training may be considered as new therapeutic strategies for cardiomyopathy in diabetes condition." (PMID 36721814, 2023). "The coexistence of diabetes could alter GH and IGF-1 levels and influence the OGTT result and the clinical judgment of biochemical remission." (PMID 37244996, 2023). "In the state of diabetes mellitus, RORα fails to upregulate as hyperglycemic inflammatory microenvironment induced IGF1‐AMPK signalling deficiency, leading to impaired bone repair." (PMID 37051760, 2023). "WSS is characterized by a variety of predominantly endocrine and nervous system abnormalities including hypogonadism, diabetes mellitus (DM; in 95% of patients), hypothyroidism, low insulin-like growth factor (IGF-1) levels, deafness, alopecia, and electrocardiographic abnormalities." (PMID 36721231, 2023). "Another mechanism through which diabetes is hypothesized to promote carcinogenesis is the insulin-like growth factor 1 (IGF-1)-mediated stimulation of cell proliferation." (PMID 36975729, 2023). "The aim of this study was to evaluate the prevalence and severity of metabolic comorbidities (diabetes, hypertension, and dyslipidemia) in surgically treated acromegalic patients with disease control and discordant GH and/or IGF-1 levels compared with those with concordant values." (PMID 37829686, 2023). "Alteration of glucose/insulin system, such as in subjects with diabetes, may increase both local synthesis and action of IGF1, leading to glomerular enlargement and progression of diabetic nephropathy." (PMID 37338602, 2023). "One of the mechanisms affecting the induction of the tumorigenesis process in diabetes is the increase in the bioavailability of the insulin-like growth factor-1 (IGF-1), which under standard conditions is responsible for lowering blood glucose levels and simultaneously diminishing insulin levels." (PMID 37373398, 2023). "Conditions such as diabetes mellitus and liver cirrhosis may alter IGF-1 values by increasing the proteolysis of the IGF-1 binding protein 3 (IGFBP-3)." (PMID 37241010, 2023). "Changes in IGF1 and IGFBP concentrations are, therefore, said to be associated with reduced insulin levels in the portal vein, as the therapeutic supply of insulin in diabetes comes through the subcutaneous route." (PMID 37859903, 2023). "In diabetes melitus, RORα was not upregulated after bone defect due to deficient upstream IGF1‐AMPK signalling, resulting in impaired bone regeneration." (PMID 37051760, 2023). "Our present study found that hyperthyroidism markedly elevates IGF-1 and, conversely, STZ-induced diabetes suppresses IGF-1 from immaturity to adult age in mice, while in the DH syndrome group, thyrotoxic treatment caused up-regulation of IGF-1 to control levels." (PMID 37654561, 2023). "In diabetes, muscle IGF-1 expression plays an important role in muscle protein synthesis." (PMID 37016292, 2023). "In the situation of diabetes, hyperinsulinemia may therefore directly enhance tumor growth and progression or indirectly promote malignant transformation through IGF-1 signaling." (PMID 36213272, 2022). "Additionally, low IGF-1 levels were associated with high fasting glucose levels in subjects without diabetes, suggesting that IGF-1 levels are a potential marker of pre-diabetes in obese patients." (PMID 36418379, 2022). "Our 2-way ANOVA evidenced a significant main effect of diabetes on serum IGF-1 levels (p<0.00001)." (PMID 36060973, 2022). "Suppression of endogenous IGF-1 in diabetes may contribute to neuropathy and its upregulation at the transcriptional level by CEBPβ can be a promising therapeutic approach." (PMID 35298717, 2022).
diabetes (continued). "Since decreased serum IGF-1 levels may be involved in decreased bone quality, combining serum IGF-1 with BMD may increase screening efficiency for risk assessments of diabetes-related osteoporosis." (PMID 36078393, 2022). "It is possible that this complex interaction between IGF-1 levels in various organs in diabetes and chronic kidney disease may explain our findings." (PMID 35976968, 2022). "Among multiple metabolic hormones in diabetes mellitus, insulin like growth factor 1 (IGF1) is found to be closely related to Aβ clearance and tau phosphorylation, suggesting IGF1 as an important mediator with a wide spectrum of effects on the pathophysiology of diabetes mellitus and AD." (PMID 35571248, 2022). "Diabetes could have a potentially protective role against PC progression by reducing the activity of insulin-like growth factor 1 and testosterone levels." (PMID 35663714, 2022). "As well as providing a response to nerve injury, there may also be ongoing IGF-1-mediated support of sensory neurons by SGC that is disrupted by insults such as diabetes and thus contributes to the pathogenesis of diabetic neuropathy." (PMID 35298717, 2022). "The notable canonical pathways shared between both CUR groups in the different dietary regimens included insulin secretion and insulin receptor signaling pathways, the senescence pathway, IGF-1, mTOR, and Hif1 α signaling, and Type 2 diabetes mellitus signaling." (PMID 35017319, 2022). "Thus, suppression of IGF-1-mediated neurotrophic support and its signaling is proposed to contribute to neurodegeneration in diabetes." (PMID 35298717, 2022). "Prevention of advanced glycation end products accumulation in the STZ-induced model of diabetes has been reported to inhibit overexpression of IGF1, IGFBP-1, and IGFBP-4 mRNAs, suggesting the role of glycation end products in activation of IGF1 renal expression in diabetes mellitus." (PMID 34943879, 2021). "Future work could address this by investigating regional heterogeneity of the effects of insulin and IGF-1 signaling on brain myelination, as well as relating insulin action to myelination in animal models of obesity or diabetes." (PMID 33669242, 2021). "In the human retina, diabetes decreases IGF1 expression and promotes a slight increase in IGF1R." (PMID 33575847, 2021). "Nevertheless, increased levels of IGF1 have also been reported in patients with diabetes mellitus." (PMID 33692752, 2021). "Finally, metabolic abnormalities especially diabetes mellitus would influence the levels of IGF-1/IGFBP-1." (PMID 35127852, 2021). "In addition, the diabetes group showed higher concentrations of serum IGF-1 compared to control and CRC group." (PMID 34208601, 2021). "It was speculated the IGF-1 function is partly affected by inflammation, oxidative stress, and diabetes." (PMID 34443530, 2021). "Another factor influencing the Cu/Zn ratio is hormone signaling, particularly the decline of insulin, GH, and IGF-1, which are all stimulators of albumin synthesis, and this decline is common in elderly or pathological conditions such as diabetes or pre-diabetes." (PMID 34066564, 2021). "In addition, dairy consumption (as measured by IGF1) was found to increase the probability of cancer by about 50%, while plant-based nutrition reduced diabetes by about 27%." (PMID 37928317, 2021). "Reports showed that medications anti-diabetic activities could alleviate bone deformities during diabetes through regulation of insulin, glucose and IGF-1 levels." (PMID 34371877, 2021). "Therefore, understanding the underlying mechanisms of OCN regulation of glucose metabolism and dissecting its interplay with insulin and IGF1 will shed light on how to use it to treat diabetes in an effective and safe manner." (PMID 34489478, 2021). "It has been speculated the function of IGF-1 was partly affected by inflammation, oxidative stress, and diabetes." (PMID 34443530, 2021).
diabetes (continued). "A cross-sectional study was conducted to measure serum levels of IGF-1 and sclerostin in 40 premenopausal women with and without diabetes mellitus using an enzyme-linked immunosorbent assay." (PMID 34690653, 2021). "Thus, the reduction of serum and vitreous IGF-2 and IGF-1 by diabetes is specific relative to the overall increase in vitreous protein and not likely because of IGF binding proteins." (PMID 33915127, 2021). "Total vitreous IGF-1 content was reduced by 50%, although diabetes increased a 17 kDa form." (PMID 33915127, 2021). "Diabetes significantly increased the rapidity of FI increase, congruent with recent research, which highlights the critical role of insulin resistance and Insulin-like Growth Factor-1 in the development of frailty." (PMID 34922488, 2021). "One of the possible mechanisms which explains this inverse association between diabetes and PC, is the low insulin concentration in long-term diabetes, resulting in lower plasma IGF-1 levels in diabetics compared to non-diabetics." (PMID 33921222, 2021). "Therefore, IGF1 levels should be assessed in patients with prostatic diseases, when diabetes (or other metabolic alterations) or acromegalic features concomitantly occur." (PMID 33692752, 2021). "Diabetes affects IGF1/IGF1R expression and signaling in several organs." (PMID 33575847, 2021). "Firstly, IGF-1 decreases the blood glucose levels and improves the situation of diabetes." (PMID 32024487, 2020). "The role of IGF-1 in DR and other diabetes complications has been extensively studied." (PMID 33905470, 2020). "The role of IGF-1 in the development of IR and diabetes complications has already been described." (PMID 33905470, 2020). "Significant inverse associations with plasma IGF1, independent of age, were observed for the prevalence of diabetes mellitus as primary renal disease, the time between transplantation and baseline measurements, the cumulative prednisolone dose, and GGT." (PMID 31973007, 2020). "Therefore, the aim of this review was to discuss a large body of evidence on the therapeutic potential of human IGF-1 in diabetes complications and to understand the mechanism and metabolic links of IGF in diabetes complications." (PMID 33905470, 2020). "The IGF-1 gene is under GH control in certain tissues such as liver, kidney, and heart, but is also responsive to factors like developmental signals, nutritional status, diabetes, aging, and neural activity." (PMID 33905470, 2020). "However, diabetes patients are also sensitive to stimulation of adverse effects in response to IGF-1." (PMID 33905470, 2020). "High serum IGF-1 predicted greater risk for MDCI (HR 1.56, 95% CI 1.08–2.26) and composite incident morbidity (HR 1.242, 95% CI 1.004–1.538), whereas high IGFBP-1 predicted lower risk for diabetes (HR 0.50, 95% CI 0.29–0.88)." (PMID 32492897, 2020). "Considering the plausible role of IGF-1 in prostate carcinogenesis and a strong link between IGF-1 and diabetes, future studies could decipher the association between pubertal timing and risk of diabetes and prostate cancer." (PMID 32439935, 2020). "Among those were IGF1 and IGF2, which already have stronger associations to diabetes." (PMID 32735660, 2020). "The results indicate that the upregulation of miR-320 in MMVEC from GK rats may be responsible for the inconsistency between the expression of IGF-1 protein and mRNA and therefore related to impaired angiogenesis in diabetes." (PMID 32692745, 2020). "Serum IGF-1 is useful for estimating the prevalence of vertebral fractures in patients with type 2 diabetes mellitus considering that decreased serum IGF-1 may be involved in the deterioration of bone quality." (PMID 31164134, 2019). "Insulin and IGF-1 actions in vascular smooth muscle cells (VSMC) are associated with accelerated arterial intima hyperplasia and restenosis after angioplasty, especially in diabetes." (PMID 31562314, 2019).
diabetes (continued). "The increase in heart size during pre-diabetes may be attributed to compensatory hyperinsulinemia and augmented TNFα which transform insulin growth factor-1(IGF-1) and lead to hyperplasia of cardiomyocytes." (PMID 30669379, 2019). "Some studies showed that IGF-1, a hormone similar in molecular structure to insulin and highly present and secreted in osteoblasts, significantly decreased in diabetes patients and animals, which could lead to the acceleration of bone resorption." (PMID 31443143, 2019). "KRG-mediated health-improving effects such as anti-cancer, anti-diabetes, and anti-inflammation effects have been reported to be related to the insulin/IGF-1 signaling (IIS) pathway, and downregulation of IIS has been reported to increase lifespan in many model organisms." (PMID 31672931, 2019). "Together, both diabetes and hypothyroidism may negatively regulate testicular development by inhibiting IGF-1 and testosterone." (PMID 29940839, 2018). "However, other reports suggest the changes across pregnancy in IGF-1 for pre-existing diabetes and GDM are different, with lower levels in pre-existing diabetes and higher levels in GDM compared with controls." (PMID 30108547, 2018). "Since IGF-1 and testosterone are essential for development, we then tested whether contemporaneous diabetes with hypothyroidism influence the body weight, testes weight and epididymal weight or not." (PMID 29940839, 2018). "Our data suggested that the increased prevalence of diabetes in patients with low sKlotho level might be related to the regulatory roles of sKlotho in insulin/insulin-like growth factor-1 (IGF-1) signaling pathways." (PMID 29900135, 2018). "Furthermore, we measured serum IGF-1 and testosterone, which are the essential factors for testicular development, to investigate the influence of diabetes and hypothyroidism." (PMID 29940839, 2018). "This implies that, in diabetes setting, impaired mTOR pathway and weakened productions of IL-15 and IGF-1, exhibit mutual effects and may reach a low-level equilibrium state, an important mechanism that causes dysfunction of DETC and defective wound repair." (PMID 29225596, 2017). "Several confounding factors may affect IGF-1 levels including body mass index (BMI), diabetes, cancer, thyroid dysfunction, inflammatory diseases and medications as corticosteroids." (PMID 29065116, 2017). "We included only control patients who had no conditions such as malnutrition, hepatic failure, chronic inflammation, diabetes or hypothyroidism which might have influenced the CSF concentrations of IGF-1." (PMID 28954393, 2017). "However, when we also adjusted for baseline levels of BMI, diabetes, and depression, higher levels IGF-1 and IGFBP-3 were still significantly related to a lower risk of frailty progression." (PMID 28609827, 2017). "IGF-1 has a main role in cell proliferation and development, and is additionally involved in the pathology of adipositas, diabetes mellitus, and hypertriglyceridemia, factors of the metabolic syndrome; its secretion is stimulated via growth hormones like estradiol." (PMID 28763032, 2017). "Additionally, some studies have implicated insulin-like growth factor 1 (IGF-1) as a shared mediator in the keratinocyte proliferation seen in psoriasis and the development of diabetes and hyperlipidemia." (PMID 28719618, 2017). "None of the controls exhibited any signs of malnutrition, hepatic failure, chronic inflammation, diabetes, or hypothyroidism (conditions which might have affected the IGF-1 levels)." (PMID 28954393, 2017). "This suggests that DT may have a bioactive potency similar to IGF-1, which increases protein synthesis in diabetes to restore muscle wasting through the activation of Akt/mTOR pathways." (PMID 29181401, 2017).